CHAER1 (cardiac hypertrophy associated epigenetic regulator 1)
Synonyms: Chaer
Gene: Long non-coding RNA gene on chromosome 4 (56,699,959 to 56,705,328, reverse strand). Ensembl gene ENSG00000288944.
Diseases named in the same sentence as CHAER1 in open-access papers:
CHAER1 is named in the same sentence as 1 disease in open-access papers, as found by Europe PMC text mining. Sharing a sentence is not in itself a finding about the gene and the disease. The quoted sentences say what the papers report.
cardiac hypertrophy (3 papers, 2018 to 2023). "Additionally, a long non-coding RNA related to cardiac hypertrophy, Chaer1, and genes related to hereditary arrhythmic disorders, including Ank2, Gpd1l, and Cacna2d1, were downregulated in the Rbm20S637A/S637A mice." (PMID 33110103, 2020).